RNU6-657P (RNA, U6 small nuclear 657, pseudogene)
Gene: Small nuclear RNA gene on chromosome 10 (94,155,639 to 94,155,745, reverse strand). Ensembl gene ENSG00000206631.
Homologues: Orthologues: chimpanzee U6 (99% identical), macaque U6 (99% identical), rat U6 (85% identical), pig U6 (83% identical), dog U6 (80% identical), rabbit U6 (77% identical). Paralogues in human: RNU6-1060P (90% identical), RNU6-1152P (90% identical), RNU6-116P (90% identical), RNU6-15P (90% identical), RNU6-211P (90% identical), RNU6-1019P (89% identical), RNU6-140P (89% identical), RNU6-25P (89% identical), RNU6-33P (89% identical), RNU6-41P (89% identical), RNU6-44P (89% identical), RNU6-455P (89% identical), and 1288 more.